CD22 (CD22 molecule)
Description:
Most highly expressed siglec (sialic acid-binding immunoglobulin-like lectin) on B-cells that plays a role in various aspects of B-cell biology including differentiation, antigen presentation, and trafficking to bone marrow. Binds to alpha 2,6-linked sialic acid residues of surface molecules such as CD22 itself, CD45 and IgM in a cis configuration. Can also bind to ligands on other cells as an adhesion molecule in a trans configuration. Acts as an inhibitory coreceptor on the surface of B-cells and inhibits B-cell receptor induced signaling, characterized by inhibition of the calcium mobilization and cellular activation. Mechanistically, the immunoreceptor tyrosine-based inhibitory motif domain is phosphorylated by the Src kinase LYN, which in turn leads to the recruitment of the protein tyrosine phosphatase 1/PTPN6, leading to the negative regulation of BCR signaling. If this negative signaling from is of sufficient strength, apoptosis of the B-cell can be induced.
Synonyms: Siglec-2; SIGLEC2
Tractability: Small molecule: a high-quality ligand is known. Antibody: an approved drug acts on it; UniProt places it where antibodies can reach, with high confidence; its Gene Ontology location is reachable by antibodies, with high confidence; UniProt predicts a signal peptide or a membrane-spanning region. PROTAC: ubiquitination databases record sites on it; its protein half-life has been measured; a small molecule that binds it is known. Other modalities: an approved drug acts on it.
Target class: Adhesion
Gene: Protein-coding gene on chromosome 19 (35,319,261 to 35,347,361, forward strand). Ensembl gene ENSG00000012124.
Subcellular location: Cell membrane
Pathways (Reactome):
Immune System: Antigen activates B Cell Receptor (BCR) leading to generation of second messengers; CD22 mediated BCR regulation; Immunoregulatory interactions between a Lymphoid and a non-Lymphoid cell
Gene Ontology:
Molecular function: protein binding; CD4 receptor binding; IgM binding; protein phosphatase binding; sialic acid binding; signaling receptor binding
Biological process: B cell activation; negative regulation of B cell receptor signaling pathway; regulation of endocytosis; cell adhesion; negative regulation of calcium-mediated signaling; negative regulation of immunoglobulin production; regulation of B cell proliferation; regulation of immune response; negative regulation of immune system process; negative regulation of signal transduction
Cellular component: early endosome; extracellular exosome; plasma membrane; recycling endosome; cell surface; cytoplasm; external side of plasma membrane; membrane; neuronal cell body membrane
Genetic constraint (gnomAD): Loss-of-function variants: 49 observed, 97.34 expected, observed/expected ratio (o/e) 0.5, 90% interval 0.4 to 0.64. The upper end of that interval is the gene's LOEUF score, 0.64, which puts it in group 2 of 6, group 1 being the genes least tolerant of losing a copy. Missense variants: 916 observed, 1,095.2 expected, observed/expected ratio (o/e) 0.84, 90% interval 0.79 to 0.88. Synonymous variants: 419 observed, 438.13 expected, observed/expected ratio (o/e) 0.96, 90% interval 0.88 to 1.04.
Homologues: Orthologues: chimpanzee CD22 (97% identical), macaque CD22 (85% identical), dog CD22 (64% identical), rabbit CD22 (64% identical), mouse Cd22 (61% identical), guinea pig CD22 (61% identical), pig CD22 (61% identical), rat Cd22 (59% identical), zebrafish si:dkey-33i11.1 (14% identical), zebrafish si:ch211-1f22.16 (13% identical), zebrafish si:ch211-1f22.8 (13% identical), zebrafish zmp:0000001289 (13% identical), and 31 more. Paralogues in human: SIGLEC16 (13% identical), SIGLEC5 (11% identical), SIGLEC7 (10% identical), SIGLEC11 (10% identical), SIGLEC10 (10% identical), SIGLEC12 (10% identical), SIGLEC8 (10% identical), SIGLEC9 (10% identical), MAG (9% identical), SIGLEC6 (9% identical), SIGLEC1 (9% identical), SIGLEC14 (9% identical), and 4 more.
Diseases named in the same sentence as CD22 in open-access papers:
CD22 is named in the same sentence as 181 diseases in open-access papers, as found by Europe PMC text mining. Sharing a sentence is not in itself a finding about the gene and the disease. The quoted sentences say what the papers report.
lymphoma (116 papers, 1995 to 2025). A malignant (clonal) proliferation of B- lymphocytes or T- lymphocytes which involves the lymph nodes, bone marrow and/or extranodal sites. "To see the impact of combination therapy on different tumors and lymphomas, we categorized them based on six major tumor-associated antigens: mesothelin, disialoganglioside GD-2, CD-19, CD-22, CD-133, and CD-30, which are present in various tumors." (PMID 38799440, 2024). "To assess the impact of combination therapy on various tumors and lymphomas, we categorized them based on six major tumor-associated antigens: mesothelin, disialoganglioside GD-2, CD-19, CD-22, CD-133, and CD-30, which are present in different tumor types." (PMID 38799440, 2024). "The various mutated RTAs were used to construct anti-CD22 immunotoxins that were then tested in a mouse lymphoma model." (PMID 29438358, 2018). "However, the phenomenon of relapse associated with CD22 diminishing in lymphoma blasts is similar to CD19 antigen loss." (PMID 33865370, 2021). "While CAR-T cell therapies targeting either CD19 or CD22 individually have shown strong anti-lymphoma effects, relapses due to antigen escape remain common." (PMID 40092990, 2025). "For example, doxorubicin was targeted to lymphoma cells using nanoparticles that were coated with high-affinity glycan ligands for CD22." (PMID 41154421, 2025). "Given the heterogeneity of tumor cells, the development of CAR-Exosomes targeting multiple targets should also be explored, mirroring the success of dual-target CAR-T cell therapies (e.g., CD19/CD22) in refractory lymphomas." (PMID 40904456, 2025). "Whereas marginal dose treatment of m971-scFv CAR-T again led to lower tumor signal than 1ug36 CD22sdCAR-T-treated mice, lymphoma growth was blocked completely in mice treated with a high dose of either CD22 CAR-T product." (PMID 38596311, 2024). "Studies have been conducted on patients receiving sequential CD19/CD20/CD22 CAR-T cell therapy post-APBHSCT in lymphoma, showing good clinical outcomes." (PMID 39200272, 2024). "In preclinical studies, all-trans retinoic acid has been used to increase folate receptor β (FRβ) in AML, while bryostatin can increase CD22 expression B cell leukemia and lymphoma cells, and it seems to prevent the emergence of low CD22 variant subclones." (PMID 39770471, 2024). "DHES0815A was compared to a CD22 ADC with the same linker-payload in the CD22-expressing lymphoma model WSU-DLCL2 (HER2-)." (PMID 38212321, 2024). "CD22-sdAb-CAR candidates showed similar CD22-dependent CAR-T expansion in vitro, although only membrane-proximal epitope targeting CD22-sdAb-CARs activated direct cytolytic killing and extended survival in a lymphoma xenograft model." (PMID 38596311, 2024). "Another CD22-CAR T, SCRI-CAR22v2, is being tested in a phase 1/2 multicenter clinical trial, PLAT-07, in pediatric and young adult patients with R/R CD22+ leukemia or lymphoma (NCT04571138)." (PMID 38711850, 2024). "It recognizes the IgG-like domain 1 of CD22 and exerts a potent cytotoxic effect on tumor cells, leading to an obvious tumor mass regression in two lymphoma-xenograft bearing models." (PMID 37821931, 2023). "Since anti-CD19 and anti-CD22 nanobodies have been developed for targeting leukemia/lymphoma cells, they can be used in nanobody-based NK cell engagers." (PMID 36761751, 2023). "Anti-CD19/CD20 and CD19/CD22 dual targeting CAR-T cells are under investigation in order to increase anti-lymphoma activity and overcome tumor immune escape." (PMID 38201473, 2023). "Glyco-engineered NK-92 cells exhibit CD22-dependent cytotoxicity to lymphoma cell lines and primary lymphoma cells from human patients." (PMID 37133224, 2023).
lymphoma (continued). "The glycoengineered NK cells represent CD22–dependent cytotoxicity against CD22+ primary lymphoma cells." (PMID 37344853, 2023). "CD22 is also upregulated in B cell tumors including most lymphomas and many leukemias, hence it is an ideal target for the ADC therapeutic approach." (PMID 36654819, 2022). "Regarding the number of clinical trials corresponding to the different targets for each tumor, CD19, CD20, and CD22 are generally considered essential targets for lymphoma and leukemia." (PMID 36261831, 2022). "The expression of CD22 on B-cell precursor ALL or lymphoma cell lines was validated via flow cytometry." (PMID 35317863, 2022). "Another anti-CD22 ADC studied in lymphoma is pinatuzumab vedotin (pina, DCDT2980S, RG-7593), containing a cleavable maleimidocaproyl-Val-Cit-PABC linker attached to the micro-tubule inhibitor MMAE with a DAR of four." (PMID 36654819, 2022). "Here, we present two cases of patients who underwent CAR-T-cell cocktail therapy with anti-CD19 and anti-CD22 CAR (CAR19/22) T cell for lymphoma." (PMID 34691067, 2021). "In summary, we have generated the first lymphoma model for testing drugs against human CD22 in an immunocompetent mouse." (PMID 34638774, 2021). "We developed a myc-driven, primary murine lymphoma model expressing a human-mouse chimeric CD22 (h/mCD22)." (PMID 34638774, 2021). "The major goal of our study was to establish an immune-competent, primary murine lymphoma model for treatment evaluation of drugs against human CD22 in an immunocompetent TME that closely reflected human disease." (PMID 34638774, 2021). "Glycoengineering of NK cells enhances their killing ability toward CD22+ lymphoma in a CD22-dependent manner." (PMID 32762681, 2020). "A and B showed the expression of CD19, CD20 and CD22 in lymphoma cells before auto-CAR T cell therapy." (PMID 30791947, 2019). "CD22, an alternative surface marker expressed by B cell leukemia and lymphoma cells, can be targeted by CAR-T therapy." (PMID 31637014, 2019). "C and D showed the expression of CD19, CD20 and CD22 in lymphoma cells before haplo-CAR T cell therapy." (PMID 30791947, 2019). "CAT-3888 (BL22), another immunotoxin, which targets the CD22 antigen on certain lymphoma cells, attached to a bacterial Pseudomonas exotoxin, PE38, has shown activity against hairy cell leukemia (HCL) in early clinical trials." (PMID 31024856, 2019). "CD20 CAR-T cells have been evaluated for efficacy and safety, and preclinical investigations have demonstrated similar anti-lymphoma activity compared to CD22 CAR-T cell therapy." (PMID 31637014, 2019). "CD22 has been validated as a successful target for B cell leukemia and lymphomas using an immunotoxin approach." (PMID 28434147, 2017). "While apoptosis induction is not considered the primary mode of action of Emab, previous in-vitro data have demonstrated that crosslinking of CD22 by mAbs including Emab induces apoptosis in human lymphoma cells." (PMID 28506291, 2017). "Building on the success of antibody drug conjugates, we developed a fusion protein consisting of a novel anti-CD22 scFv and apoptin and tested binding and therapeutic effects in lymphoma cells." (PMID 28582973, 2017). "Overall, the novel DOX–platelet–CD22 drug delivery system offers a promising new therapeutic option for lymphoma." (PMID 28938559, 2017). "In the present study, we took the advantages of both CD22 as a target antigen and apoptin as a cytotoxic moiety to generate a novel antibody conjugate to target CD22 positive leukemia and lymphoma cells." (PMID 28582973, 2017). "In this study, we developed a novel drug delivery system for lymphoma treatment: DOX-loaded platelets that were conjugated with anti-CD22 monoclonal antibodies (mAbs) (DOX–platelet–CD22)." (PMID 28938559, 2017). "Herein, we used mAbs against CD22 as a delivery vehicle to precisely direct DOX-loaded platelets to tumor sites for the treatment of lymphoma." (PMID 28938559, 2017).
lymphoma (continued). "In this study we employed amphibian RNase ONC as effector moiety for creating a novel protein-protein ADC to target CD22-positive leukemia and lymphoma cells." (PMID 26605343, 2015). "After conjugation to the murine anti-CD22 IgG2a-mAb LL2, ONC caused only mild off-target toxicity in lymphoma xenografted mice, and the toxic total cumulative dose (TCD) was reached only at concentrations of >300 mg/kg body weight." (PMID 26605343, 2015). "Using a capture assay for pharmacokinetic characterization, immobilized anti-idiotype scFv Hc5 (then named as LRID03) was used as a surrogate ligand for CD22 to determine the serum levels of residual SM03 in lymphoma patients treated with the antibody." (PMID 24816427, 2014). "Despite lower CD22 expression on ALL cells compared to lymphoma cells, IO had similar cytotoxicity against both types of cells in preclinical in vitro studies." (PMID 24795859, 2014). "CD22 is of particular interest as it is a target approved for monoclonal antibody therapy in several B-cell leukemias and lymphomas." (PMID 24130782, 2013). "The humanized anti-CD22 mAb Epratuzumab conjugated to SAP is specifically cytotoxic to CD22+ lymphoma cell lines, being able to completely eliminate target cells while sparing non-target cells." (PMID 22069735, 2011). "Our findings suggest that LoopCAR-1 could be a promising therapeutic option for B-ALL or lymphoma patients with CD19 or CD22 expression." (PMID 38823002, 2025). "Immunotherapies targeting CD22, including unmodified or drug-conjugated anti-CD22 antibodies and chimeric antigen receptors against CD22, have been developed as treatments against B cell leukemia and lymphoma." (PMID 40054694, 2025). "For example, upregulated proteins such as HLA-DRB1, CD22, CD74, and CD8A are consistent with established roles in lymphoid malignancies and oncogenic signaling, supporting prior studies identifying CD74 as a diagnostic and therapeutic target in lymphomas." (PMID 41035678, 2025). "Not strictly a CAR-NK, the engineered NK-cells could effectively bind to CD22-positive lymphoma cells and exert cytotoxicity in preclinical models." (PMID 38711850, 2024). "A B cell lineage was confirmed for 1 dog with a CD21−/CD22+ lymphoma/leukemia in the bone marrow on the basis of a clonal B cell population on polymerase testing for antigen receptor rearrangements (PARR) and CD20+/CD3− cells on immunocytochemical staining of bone marrow smears." (PMID 39224452, 2024). "Noting the partial CD19 expression on the BL cells at the time of lymphoma progression, 1922zT2 T cells used in this study, incorporating humanized scFvs targeting both CD19 and CD22, may have reduced the risk of antigen escape." (PMID 39717765, 2024). "Upregulation of CD22 expression by bryostatin-1 pretreatment could potentially re-sensitize lymphoma cells to CD22-CAR T." (PMID 38711850, 2024). "Since 223Ra cannot be reliably chelated and then coupled to binding vector molecules, its parent nuclide thorium-227, with a half-life of 18.7 days, was used in a first human clinical trial for targeted alpha therapy with monoclonal antibodies against CD22 in lymphomas." (PMID 38256909, 2024). "Furthermore, CD16(scFv)/CD19/CD22(scFv) TriKE was developed for targeting CD19 and CD22 (leukemia/lymphoma antigens) and CD16, simultaneously." (PMID 36761751, 2023). "Moreover, the chidamide-mediated upregulation of CD22 on lymphoma cells intensified the antitumor response from CD22-specific CAR-T cells." (PMID 36768665, 2023). "Finally, the histone deacetylase inhibitor (HDACi) chidamide, which is capable of broadly modulating gene expression in B-cell lymphoma cell lines, was found to significantly upregulate CD22 expression in lymphoma cell lines in vitro and in vivo." (PMID 36768665, 2023).
lymphoma (continued). "With a DAR of 1.74, epratuzumab-cys-tesirine shows potent and specific in vitro and in vivo activity against different CD22-expressing human lymphoma models (Ramos, Daudi, WSU-DLCL2, and SU-DHL-4), inducing DNA inter-strand cross-linking after a 2-h exposure period." (PMID 36654819, 2022). "Moreover, in some patients the CD19 downregulation is accompanied by decreased expression of other surface antigens, such as CD20 and CD22 in B-ALL and similarly CD20, CD22, and CD79a in lymphomas." (PMID 35681499, 2022). "The anti-CD22 scFv proved to be specific in CD22+ lymphoma cell lines." (PMID 36077739, 2022). "CD22 is another popular target when designing CAR-T therapy for lymphoma." (PMID 35602947, 2022). "In line with this efficacy of Moxetumomab in immunocompromised xenografts of human lymphoma, HF injections were more active than bolus doses in our h/mCD22+, primary murine lymphoma, thus indicating functional similarity of human CD22+ lymphoma and the newly established h/mCD22+ murine lymphoma." (PMID 34638774, 2021). "Importantly, CD19-negative or -low leukemia or lymphoma cells retain expression of other B cell markers such as CD22 for B-ALL, CD20 and CD79a for lymphoma." (PMID 34809678, 2021). "CD16-directed BiKEs CD16 × CD19 and CD16 × CD33 and TriKE CD16 × CD22 × CD19 were shown to specifically stimulate NK cell activation via CD16, which triggers NK cell cytolytic activity and secretion of cytokines to attack CD19+, CD33+, and CD19+CD22+ lymphoma and leukemia, respectively." (PMID 33505304, 2020). "Target CD22+ human Daudi lymphoma cells could internalize this recombinant scFv with absolute immunospecificity as demonstrated by competitive inhibition by the parental monoclonal CD22 antibody." (PMID 29438358, 2018). "Therefore, targeted chemotherapy that is mediated by DOX–platelet–CD22 is a promising option for lymphoma treatment." (PMID 28938559, 2017). "The ability of the ITs to kill lymphoma cells was tested in the CD20-/CD22-positive Raji cell line." (PMID 28556822, 2017). "Moreover, our data revealed that the number of attached ONC payloads is crucial for achieving significant in vitro cytotoxicity towards CD22-positive lymphoma and leukemia cell lines." (PMID 26605343, 2015). "Importantly, the anti-idiotype scFv Hc5 was target-specific with high affinity, and was successfully used for pharmacokinetic analysis of circulating residual antibody in lymphoma patients treated with the idiotype anti-CD22 antibody SM03." (PMID 24816427, 2014). "Moreover, efforts have been made to demonstrate the anti-idiotype scFv antibody acting as a surrogate antigen for membrane protein CD22, and its application in monitoring serum anti-CD22 antibody in lymphoma patients treated with the anti-CD22 antibody." (PMID 24816427, 2014). "Finally, we evaluated the internalization property on human lymphoma cell line of the anti-Human CD22 hLL-2 MAb, already used in phase I/II clinical trials for DLBCL treatment in humans, to obtain an element of comparison with the internalization property of the anti-CD22c MAbs." (PMID 32117707, 2020). "Of the eighteen patients enrolled in the phase I/II study with CD19 or CD22 positive lymphoma or leukemia, one patient with primary refractory pre-B acute lymphoblastic leukemia achieved complete tumor response after one cycle and two patients with lymphoma experienced partial responses." (PMID 32630411, 2020). "Moreover, our results also demonstrated firstly that the anti-idiotype scFv could be used for pharmacokinetic measurement of circulating residual antibody in lymphoma patients treated with chimera anti-CD22 monoclonal antibody SM03." (PMID 24816427, 2014). "In lymphoma models resistant to rituximab (RTX), an anti-CD20 antibody, LILRB1 levels tended to increase, while CD20 was downregulated, and CD22 and CD19 remained largely unchanged." (PMID 40186066, 2025).